TET1 (tet methylcytosine dioxygenase 1)
Diseases named in the same sentence as TET1 in open-access papers (continued):
Sharing a sentence is not in itself a finding about the gene and the disease.
tumor (continued). "They focus on ‘ten-eleven translocation 1’ (TET1) which is an important regulator of 5-hydroxymethylcytosine (5hmC) in embryonic stem cells, and the loss of 5hmC in many tumours suggests a critical role for the maintenance of this epigenetic modification." (PMID 26146524, 2015). "In the present study, we analyzed patients’ clinicopathological characteristics and the levels of mRNAs encoding TET1–3 and TDG proteins that were present in tumor tissue." (PMID 26207381, 2015). "In human HCC, a decreased 5hmC was associated with disease progression through down-regulation of TET1, while high 5hmC and IDH2 levels were associated with a favorable prognosis following tumor resection." (PMID 25918251, 2015). "TET1 protein acts as tumor suppressor gene regulating critical pathways involved in cell proliferation and tumor metastasis." (PMID 24939750, 2014). "In particular, TET1 acts as tumor suppressor preventing cell proliferation and tumor metastasis and it has frequently been found down-regulated in cancer." (PMID 24939750, 2014). "Such an observation highlights the importance of tissue context in understanding a gene’s function since TET1 can act as a tumor suppressor in solid tumors, but as an oncogene in leukemogenesis." (PMID 24172544, 2013). "TET1 has also been shown to be a tumor suppressor in various cancers, including prostate and breast cancers." (PMID 24172544, 2013). "Previous studies demonstrated that the decrease level of 5 hmC in tumors was due to the reduced expression of TET1/2/3 and IDH2 genes or tumor derived IDH1 and IDH2 mutations." (PMID 23671639, 2013). "This study aimed to evaluate whether the dual delivery of DNMT inhibitors and pDNA of TET1 could synergistically enhance tumor suppressor gene expression and induce cell cycle arrest and/or apoptosis in cancer cells." (PMID 39982248, 2025). "For example, TET1-mediated demethylation of tumor suppressor miRNA promoters can reactivate their expression, inhibiting tumor progression, while demethylation of oncogenic miRNA promoters may promote malignancy." (PMID 40520993, 2025). "Interestingly, while most studies reported low TET expression in tumors, positioning TET proteins as tumor suppressors, one study identified TET1 as a potential oncogene." (PMID 40014756, 2025). "Additionally, TET1 plays a key role in inhibiting tumor progression, but its effects vary across different tumors." (PMID 40520993, 2025). "Additionally, miR-49485 and miR-520b86 were found to promote tumor vascular invasion and suppress proliferation in liver cancer cells, respectively, by targeting TET1." (PMID 40520993, 2025). "In HCC, the expression of TET1 is significantly higher in tumour samples than in normal tissues." (PMID 39823268, 2025). "Moreover, TET1 inhibits tumor cell invasion by maintaining the expression of tissue inhibitors of metalloproteinases (TIMP) and MMP." (PMID 40599235, 2025). "Targeting TFF1, PPA1, DKK1, LGR6, and MARCH1—while considering the tumor-suppressive role of TET1—may offer novel therapeutic avenues to overcome chemoresistance and improve patient outcomes." (PMID 40862711, 2025). "Mouse models further confirm that TET1 overexpression inhibits tumor growth." (PMID 40862711, 2025). "Inhibiting TET1 or activating TET2 was found to reverse tumor progression." (PMID 40520993, 2025). "Conversely, DNMT1-mediated methylation silences chemokines such as CXCL9 and CXCL10, leading to reduced anti-tumor immune cell infiltration; the restoration of TET1 and TET2 can reverse this effect and improve the efficacy of immune checkpoint inhibitors (ICIs)." (PMID 41394878, 2025). "As a prognostic risk factor and most mutated gene, TET1 strongly inversely correlated with cytotoxic lymphocyte infiltration, which include CD8+ T cells and CD56dim NK cells, and positively correlated with Th2, which mostly related to tumor-promoting actives." (PMID 38736884, 2024).
tumor (continued). "Recent study demonstrated that Tet1 exerted tumor suppressive effects in CRC cells." (PMID 38271970, 2024). "For example, TET1 expression and 5hmC levels are decreased in tumor samples from luminal A, luminal B, and HER2-positive subtypes compared to normal breast tissue samples and correlate with larger tumors, advanced stage, lymph node status, and poor patient survival." (PMID 38645113, 2024). "Western blotting showed that TET1 protein expression increased along with YAP1 expression in mst1/2 mutant mice tumor tissues, which suggests that TET1 expression may be regulated by YAP1 in HCC cells." (PMID 38967794, 2024). "One of them, SFRP2, is a member of the secreted frizzled-related protein (SFRP) family and a typical regulatory protein of the WNT pathway; it has been reported as a co-factor for ten-eleven translocation 1 (TET1), contributing to the inhibition of tumor metastasis." (PMID 38069266, 2023). "TET1 has been recognized as a tumor suppressor in a variety of human cancer." (PMID 37430206, 2023). "Additionally, the decreased TET protein family, in particular, TET1 was the main factor that reduced the 5-hmC in the tumor tissues of HBV-infected HCC." (PMID 37266610, 2023). "Our results indicated that miR-183-5p could act as a tumor promoter in PCa and it accelerated the malignant progression of PCa by directly targeting and down-regulating TET1." (PMID 37430206, 2023). "Furthermore, Quantitative real-time PCR results demonstrated that TET1 was downregulated in 54.02% of human colorectum tumor tissues, compared with levels in adjacent normal tissues (Normal: 0.01357 ± 0.00070 vs. Malignant: 0.00733 ± 0.00046, p < 0.0001)." (PMID 36966142, 2023). "TET1 was significantly higher expressed in tumor samples than that in normal samples." (PMID 37181808, 2023). "Interestingly, we found that HIF1α expression, rather than HIF2α expression, was significantly decreased in tumor tissues of Brafm/+; Tet1−/− mice compared with that of Brafm/+; Tet1+/+ mice." (PMID 37020036, 2023). "The tumor suppressor role of TET1 has been controversial, however." (PMID 37020036, 2023). "The role of TET1 in apoptosis has been the subject of multiple studies involving tumor cell lines." (PMID 37371754, 2023). "Moreover, this down-regulation of TET1 expression impaired TET1-dependent demethylation reactions to epigenetically silence the TFPI2 tumour suppressor gene." (PMID 35389425, 2023). "The expression of TET1 and 3 did differ between tumor and paired normal tissue in pN+ tumors." (PMID 37367043, 2023). "The tumor-suppressive role of TET1 in B-cell malignancies has been well-documented." (PMID 36203205, 2022). "By analyzing the abundance of tumor-infiltrating immune cells, we found that the CD8+ T cells, B cells, myeloid dendritic cells, and neutrophils were more abundant in TET1-mutated patients than in TET1 wild-type patients." (PMID 35395805, 2022). "Under normal conditions, PROSER1 might carry out a tumor-protective role by clearing DNA methylation from these CGIs through its regulation of TET1/2." (PMID 34667079, 2022). "From imbalance between down-regulation of DNMTs and of the DNA demethylases TET1, having opposite roles in controlling DNA methylation, it may result that miR-29b acts as a tumor suppressor or as an oncogene, depending on cell conditions." (PMID 36140539, 2022). "In the MMTV-Py-MT model (luminal tumors), qRT-PCR revealed low levels of exon 1 (Tet1 long isoform) in tumor tissue and a twofold increase expression level of the shorter Tet1 gene in tumor tissue suggesting the possible relevance of this isoform in breast tumorigenicity in specific tumor types." (PMID 35646706, 2022). "The tumor-promoting role of TET1 has been reported in both myeloid and T-cell malignancies." (PMID 36203205, 2022). "Also, our results demonstrate a correlation between the differentiation level of the tumor and TET1 level, where high level of TET1 accompanies higher level of differentiation." (PMID 35646706, 2022).
tumor (continued). "In addition, we noticed that the expression level of TET1 correlates with the degree of differentiation of the tumor." (PMID 35646706, 2022). "In their study, they revealed that hypoxia conditions could upregulate TET1/3 expression via HIF1α and in turn increase the 5hmC level in tumor cells." (PMID 34885145, 2021). "Furthermore, we also conduct experiments to explore molecular mechanisms mediated by TET1 in tumor growth." (PMID 34926132, 2021). "Remarkably, TET1-high PCa were more frequently detected among advanced tumor stages." (PMID 34844636, 2021). "Further analyses showed that TET1-high PCa specimens were more frequently detected among PCa with higher Gleason scores (Gleason 6: 8.4%, Gleason 7: 13.3%, Gleason 8: 20.5%, Gleason ≥ 9: 17.6%) and higher tumor stages (T2a–c: 11.5%, T3a–b: 16.6%, T4: 40%)." (PMID 34844636, 2021). "Using this model, we demonstrate that leukemic transformation by MLL-ENL in vivo and in vitro was not critically affected by the Tet1-ablation, although the expression of Evi1, which is one of critical target genes of MLL fusion gene, in tumor cells was remarkably low under Tet1-ablated condition." (PMID 33705482, 2021). "In xenograft models, TET1 depletion promotes tumour cell growth, invasion and metastasis." (PMID 34656178, 2021). "TET1 is also critical in maintaining the differentiation pluripotency of embryonic stem cells and plays anti- or oncogenic roles in combination with different signalling pathways in different tumours." (PMID 34656178, 2021). "In addition, further investigation to demonstrate the relationship of overexpressed TET1 and tumor-specific 5hmC signature is needed." (PMID 33926529, 2021). "To determine whether abrogation of Tet1 expression attenuates tumor cell growth, we used small hairpin RNA (shRNA) targeting of Tet1 in primary cell cultures of SmoA1-MBs." (PMID 33926529, 2021). "Results of xenografting prove that downregulation of TET1 inhibits tumor growth in vivo." (PMID 34926132, 2021). "TET1 is usually known as a tumor suppressor, which could inhibit cancer progression via various pathways." (PMID 34957093, 2021). "Notably, TET1 as a tumor suppressor of B‐cell malignancy has also been supported by evidence of reduced TET1 expression in human non‐Hodgkin's lymphomas." (PMID 36618446, 2021). "In conclusion, our results suggest that in PCa, TET1-expressing cells and cell colonies may be proliferating tumor cells with a distinct oncogenic signature." (PMID 34844636, 2021). "TET1 is generally considered a tumor suppressor, while it is often down-regulated in multiple malignancies including breast, hepatic, pancreatic, gastric, and prostate cancers, but it has also been reported as a potential oncogene that contributes to aberrant hypomethylation in cancer." (PMID 34731191, 2021). "Recent studies suggest that TET1 is differentially expressed in different types of tumours and different subtypes of the same tumour and exhibits different biological effects by activating different genes in different signalling pathways, thus displaying both oncogene and antioncogene properties." (PMID 34656178, 2021). "In the TCGA dataset, TET1-MUT was strongly associated with higher tumour mutational burden and neoantigen load, as well as inflammatory patterns, immune features and immune-related gene expression in tumour-infiltrating T lymphocytes." (PMID 34656178, 2021). "In addition, under the action of EVs circ‐0000190, tumour growth was impeded and the expression of TET1 was inhibited via the competitive binding to miR‐767‐5p." (PMID 31923350, 2020). "Taken together, the results suggested that the downregulated expression of TET1 might be correlated with the low expression of 5hmC and exerted a tumor-suppressive function in the BCPAP cell line." (PMID 32089682, 2020). "TET1, as DNA demethylase, is thought to be related to tumor metastasis." (PMID 33109235, 2020).
tumor (continued). "In our study, based on the ceRNA hypothesis, tumor-promoting genes, including KCNQ1OT1, JARID2, CDK6, DNMT3A, and TET1, competitively bound the tumor suppressor gene hsa-29c-3p." (PMID 32127798, 2020). "We also examined whether AJAP1 is a critical regulator of TET1-induced tumor suppression and inhibition of Wnt/β-catenin pathway." (PMID 32528872, 2020). "We conclude that in T-ALL, MYC-driven overexpression of TET1 contributes to tumor cell-specific 5mC and 5hmC patterns and thus gene expression programs that are important for enhanced global protein synthesis and tumor cell proliferation." (PMID 31266538, 2019). "Indeed, we found that TET1 KD or ectopic expression of TET2 decreased cell proliferation in T-ALL and was associated with genome-wide changes in 5mC and 5hmC, suggesting a tumor promoting function of TET1, and a tumor suppressing role for TET2." (PMID 31266538, 2019). "In vitro migration and invasion assays were performed to explore whether TET1 inhibited the migration and invasive capacity of tumor cells." (PMID 31153371, 2019). "IHC showed an increased expression of tumour TET1 protein in the EnzR-C4-2 circUCK2 group." (PMID 31844675, 2019). "The in vitro proliferation assay exhibited the tumor-suppressive function of TET1." (PMID 31399111, 2019). "In addition to tumor proliferation, we also investigated the role of TET1 in pancreatic cell migration, invasion, and EMT through wound healing and transwell assays." (PMID 31399111, 2019). "We next sought to investigate whether TET1 knockdown transcriptionally inhibits tumor suppressor gene expression in HCC cells." (PMID 31153371, 2019). "However, the molecular mechanism of the induction of TET1 and its role in tumor progression are still obscure." (PMID 31153371, 2019). "As EMT plays an important role in initiating tumor metastasis, to confirm whether TET1 suppresses migration and invasion by inhibiting EMT, we compared the levels of E-cadherin, an EMT marker, in cell lines by western blotting." (PMID 31399111, 2019). "For one additional tumor almost all cell nuclei stained positive for TET1." (PMID 30045709, 2018). "The expression of TET1 showed a trend of up-regulation only in the GBM0.2 tumours." (PMID 30208958, 2018). "At the 54th day after a single transfection, subcutaneous tumors were taken out from the nude mice, and the weight of the subcutaneous tumor taken out from the nude mice treated with TET1-CD was obviously lighter than that from the nude mice treated with TET1-mCD and empty vector." (PMID 30551127, 2018). "As there was a higher percentage of hyper-DMRs in the GBM0.2 tumours, the up-regulation of TET1 might be a response to counter the increased hyper-methylation observed." (PMID 30208958, 2018). "Also, in several tumor samples, consecutive sections were used for staining because the three antibodies specific for 5hmC, TET1 and TET2 shared the same host and hence double immunofluorescent staining was not possible to perform." (PMID 30045709, 2018). "In the meantime, the reduced methylation status of DACT2, Wnt5A, and SFRP2 promoter was detected in TET1-CD-expressing tumor cells, with increased unmethylated sites at the promoter CpG regions, suggesting that TET1 really acts as a demethylase to renew expression of multiple TSGs in tumor cells." (PMID 30075814, 2018). "We found that both pH2AX and cleaved caspase 3 were highly expressed in TET1-overexpressing tumor." (PMID 29156803, 2017).
tumor (continued). "Thus we can conclude that 3,6-DHF inhibits DNMT1 activity, modulates the imbalance of DNA methylation and demethylation status, increases TET1 expression, re-expresses miR-34a, and as a consequence, prevents breast carcinogenesis." (PMID 28870206, 2017). "Moreover, suppression of TET1 expression was reported to be associated with facilitated cell invasion and metastasis and even to play a critical role in KRAS-induced tumour transformation." (PMID 28228863, 2017). "Additionally, we observed a significant increase in RASSF5 levels in TET1-overexpressing tumor tissue samples." (PMID 29156803, 2017). "Furthermore, the roles of TET proteins in the regulation of cancer progression are probably different in that TET1 is primarily involved in tumor initiation while TET2 and TET3 are primarily involved in cancer metastasis." (PMID 27852070, 2017). "Moreover, TET1 inhibits tumor development and invasion partly via maintaining the expression of tissue inhibitors of metalloproteinase (TIMP) dependent of its catalytic activity." (PMID 27557497, 2016). "TET1 protein levels were reduced in tumor versus non-tumor prostate tissue in 39 of 40 cases." (PMID 27014907, 2016). "A dot blot assay of the tumor DNA from the patient with the mutated TET1 indeed contained less 5hmC than non-tumor tissue." (PMID 27014907, 2016). "Meanwhile, it suggested TET1 as tumor suppressor in colon cancer." (PMID 27183914, 2016). "In DIPG, TET proteins (TET1 and TET3) and 5hmC may underlie the tumor formation and resistance to treatment." (PMID 27557497, 2016). "More recently, TET1 has been identified as a tumor suppressor in hematopoietic malignancy as well." (PMID 26861406, 2016). "Immunohistochemical staining (IHC) also showed TET1 down-regulation in tumor tissues." (PMID 27121319, 2016). "The TET1 enzyme has not been discussed in previous PCa sequencing papers, although it has been associated with PCa or suggested to act as a tumor suppressor." (PMID 27014907, 2016). "TET1 mutations in hematopoietic malignancy have a much lower frequency than TET2 mutations and their deletions cause different tumor types, suggesting that TET1 and TET2 are non-redundant and lineage-specific." (PMID 26861406, 2016). "Furthermore, we found low expression of TET1 is associated with PTEN loss and more AKT phosphorylation in the tumor specimens." (PMID 27121319, 2016). "As tumor suppressor, TET1 suppression in GC was attributed to promoter hypermethylation of TET1." (PMID 27183914, 2016). "They conclude that TET1 acts as a tumour suppressor of B-NHL." (PMID 26146524, 2015). "More specifically, interacting partners of PARP-1 responsible for its recruitment and/or activation on TET1 gene may be deregulated in specific tumor cell lines thus affecting PARP-1 positive regulation of TET1 transcription." (PMID 24939750, 2014). "Additionally, in an independent set of DIPG tumor samples, TET1 and TET3 mRNAs were found to be overexpressed relative to matched normal brain." (PMID 24894482, 2014). "Decreased 5hmC levels secondary to TET1 expression levels have been identified in liver adenoma, breast carcinoma, lung carcinoma, and pancreas carcinoma, and have been clinically correlated with hepatocellular carcinoma tumor size and decreased survival." (PMID 24152442, 2013). "Together, these results imply a tumor suppressor role for TET1 and TET2." (PMID 24152442, 2013). "All these results suggest that TET1 may serve as both an oncogenic role and a tumor suppressor." (PMID 37430206, 2023). "However, in addition to its such tumor suppressor functions, emerging evidence shows that TET1 can also induce the expression of a series of oncogenes dependent or independent of its dioxygenase activity, suggesting the existence of its non-enzymatic functions." (PMID 37020036, 2023). "However, both tumor-promoting and tumor-repressive functions of TET1 and TET3 have been reported." (PMID 36203205, 2022).